GSN (gelsolin)
Diseases named in the same sentence as GSN in open-access papers (continued):
Sharing a sentence is not in itself a finding about the gene and the disease.
neurological disorders (3 papers, 2018 to 2022). "A similar decrease in Gelsolin protein levels was detected in the CSF of patients with MS when compared to samples obtained from individuals with other neurological disorders." (PMID 35135578, 2022). "One downregulated protein is gelsolin, whose plasma concentration is decreased in inflammatory diseases as well as in neurological disorders." (PMID 36293192, 2022).
adenocarcinoma (2 papers, 2022). A common cancer characterized by the presence of malignant glandular cells. "Gelsolin (GSN), an actin severing protein, is described as important for CFTR activation but it is also regulated by β-catenin to promote adenocarcinoma cell migration." (PMID 35500936, 2022).
heart disease (2 papers, 2013 to 2018). "If a substantial proportion of all miR-133a isomiRs expressed in normal myocardium is miR-133a(v) (as suggested by our data) then the downregulation of this variant could contribute to the upregulation of gelsolin in heart disease." (PMID 23799049, 2013). "To test the role of gelsolin in mediating heart disease in the setting of reduced PI3Kα function, we next generated double-mutant mice by intercrossing the dominant-negative PI3Kα (PI3KαDN) mice with GSNKO mice, generating PI3Kα dominant-negative GSNKO double-mutant (PI3KαDN/GSNKO) mice." (PMID 30568254, 2018).
mitochondrial disease (1 paper, 2022). "In evidence, combining GDF-15 with gelsolin plasma levels performed even better to differentiate patients with mitochondrial disease than the combination with FGF-21 (AUC 0.94 vs. 0.91)." (PMID 36361969, 2022).
GSN also shares sentences with these, for which no sentence is quoted: myonecrosis (4 papers); acute liver failure (3); ductal carcinomas in situ (3); esophageal squamous cell carcinoma (3); thymoma (3); acute myocardial infarction (2); adenoma (2); adult respiratory distress syndrome (2); amyotrophic lateral sclerosis (2); bladder urothelial carcinoma (2); brain inflammation (2); cervical squamous cell carcinoma (2); chronic pancreatitis (2); genetic disease (2); Hepatic fibrosis (2); lung adenocarcinoma (2); neuropathy (2); pancreatitis (2); prostate adenocarcinoma (2); retinitis pigmentosa (2); acute leukemia (1); Airway obstruction (1); alcohol use disorders (1); anemia (1); ankylosing spondylitis (1); anterior ischemic optic neuropathy (1); aortic aneurysm (1); Ataxia (1); atypical ductal hyperplasia (1); autosomal dominant disease (1).
A further 84 diseases each share a sentence with GSN in 1 paper.